RNU6-784P (RNA, U6 small nuclear 784, pseudogene)
Gene: Small nuclear RNA gene on chromosome 4 (70,703,018 to 70,703,123, reverse strand). Ensembl gene ENSG00000207058.
Homologues: Orthologues: chimpanzee U6 (100% identical), macaque U6 (95% identical), dog U6 (75% identical). Paralogues in human: RNU6-43P (89% identical), RNU6-11P (85% identical), RNU6-356P (85% identical), RNU6-37P (85% identical), RNU6-80P (85% identical), RNU6-97P (85% identical), RNU6-1216P (84% identical), RNU6-1227P (84% identical), RNU6-140P (84% identical), RNU6-154P (84% identical), RNU6-21P (84% identical), RNU6-24P (84% identical), and 1286 more.